CCR7 (C-C motif chemokine receptor 7)
Diseases named in the same sentence as CCR7 in open-access papers (continued):
Sharing a sentence is not in itself a finding about the gene and the disease.
tumor (continued). "Similarly, CCL21/CCR7 axis has been shown to promote MMP-9 release, stimulate tumor cell survival, adhesion, invasion, and metastasis in HNSCC." (PMID 33925575, 2021). "Not surprisingly, there was a larger naïve population (CCR7+CD45RA+) compared to the tumour, 13.2 ± 5.47% vs. 6.56 ± 3.75%." (PMID 33917832, 2021). "Together, despite some T-ALL patients showing low or absent expression of CCR7 in their tumor cells from BM, the herein presented evidence supports CCR7 as a key element responsible of high-risk features such as CNS infiltration." (PMID 34778050, 2021). "This crosstalk was necessary for the creation and preservation of protective niches in LN and spleen as demonstrated in vivo in adoptive transfer experiments since lack of CCR7 delayed disease onset and tumor burden." (PMID 33841445, 2021). "Indeed, the CCR7/CCL21 axis promotes the growth and metastasis of many tumour types, including melanomas, breast, thyroid, colon, head, and neck cancers." (PMID 34298676, 2021). "Tumor-draining lymph node (TDLN) cells were collected after 48 h of NLGP treatment and found higher per-cell MHC-I expression along with increased CD80 and CCR7 in comparison to control (Figures 5A1,A2, also in contralateral lymph node and tumor)." (PMID 32211313, 2020). "For further validation, BmDCs Figure S5BA; optimum upregulation in 32 h; Figure S5BB) were exposed to tumor-conditioning media (TCM) to mimic tumor milieu, and upregulated MHC-I, CD80, and CCR7 expression was observed (Figures 5B1,B2) following NLGP supplementation (CD11c+ cells 77.77–89.93%)." (PMID 32211313, 2020). "Further, CD103+ DCs are a distinct DC population that is uniquely dependent on IRF8 and Batf3 transcription factors and predominantly expresses CCR7 in human tumors, expression of which was used as a molecular proxy for CD103+ DCs in clinical tumor gene expression data sets." (PMID 32759497, 2020). "Mice lacking CCR7-expressing cDC1 failed to recruit CD8+ T cells to the tumor, and the T cells that were present in the tumor microenvironment failed to proliferate, leading to an overall lack of immune control." (PMID 32508825, 2020). "The function of CCR7/CCL21 in cancer appears to be controversial; it may play a pro- or anti-tumor function depending on where it is expressed." (PMID 32340161, 2020). "Kim CG identified lower frequencies of effector/memory subtypes (CCR7- CD45RA-) in CD8+ T cells and higher frequencies of severely exhausted cells (TIGIT+) in tumor-reactive PD-1+ CD8+ T cells to predict HPD, with the area under the curve reaching 0.926 and 0.938." (PMID 32727409, 2020). "Nonetheless, log-rank tests showed no statistical differences between the survival curves of both groups, and anti-CCR7 therapy did not significantly influence the presence of tumor cells in the tissues." (PMID 33110606, 2020). "CCR7 expression on CD4+ T cells of healthy subjects and tumor patients remained stable over age, but its expression was significantly lower in tumor patients (p < 0.01) as compared to healthy volunteers and in TIL compared to PBL of tumor patients (p < 0.05)." (PMID 32082401, 2020). "The CCL21/CCR7 interaction is positively correlated with T cells chemotaxis in shaping TME, which can enhance the homing of CCR7-expressing T cells and response to systemic anti-tumor immunotherapy 165-167." (PMID 32483450, 2020). "Using total protein from HCC827 xenograft tumour tissues, we found that Afatinib inhibited the phosphorylation of JAK1,2, STAT3, and FAK, the protein expression of LYVE-1, VEGFR2, VEGFR3, VEGFC, VEGFA, and CCR7." (PMID 31892990, 2020). "Furthermore, CCL19/CCR7, CXCL12/CXCR4, and CCL20/CCR6 were shown to be potential new targets for tumor gene therapy in type 2 PRCC." (PMID 32775427, 2020).
tumor (continued). "Chemokines and their receptors play an important role in directing cognate T-APC interactions in lymph nodes and spleen (e.g., CCR7 and CCL21/19), or in bone marrow (e.g., CXCR4 and CXCL12 (SDF-1α/β), or attracting Treg cells towards tumor tissue (e.g., CCR2 and CCL2 (MCP-1))." (PMID 32155856, 2020). "In contrast to DCs, photoconversion experiments demonstrated that tumor-infiltrating T cells do not require CCR7 to migrate to dLNs via afferent lymphatics." (PMID 31191539, 2019). "Likewise, tumor-bearing Rnf5−/− mice had enhanced frequency of CCR7+ DCs isolated from GALT and of CCR7+ mDCs isolated from MLN, compared with those isolated from the WT tumor-bearing mice." (PMID 30940817, 2019). "Tumour infiltrating lymphocytes have higher expression of CD69 and lower expression of CCR7." (PMID 29587679, 2018). "Furthermore, the expression of CCR7 was significantly lower on ILC1 (p value: 0.008) and ILC3s (p value: 0.02) isolated from GI tumor tissue when compared to blood." (PMID 29587679, 2018). "Hence, differential CCR7 expression after ICAM-1 blockade is transient and occurs in tumor stroma infiltrating lymphocytes." (PMID 30258446, 2018). "So we hypothesized that the CCL19 secreted by CRC cells predominantly combined with CCR7 expressed by HUVEC and affect tumor angiogenesis." (PMID 30250188, 2018). "Moreover, we demonstrated that CCL19‐induced AKT phosphorylation; however, CCR7 siRNA suppressed CCL19‐induced AKT phosphorylation, a key regulator of tumor metastasis." (PMID 28378417, 2017). "Since, induced FoxP3 are downregulated for CCR7 and CD62L as well as upregulated for memory or effector-type trafficking receptors such as CCR4, CCR5, CCR8, CCR10, and/or CXCR4, they can migrate into the tumor via the tumor-draining lymph nodes." (PMID 29450136, 2017). "Positive staining for CCR7 was detected in tumor cells within such invasive areas but not in tumor cells in noninvasive areas." (PMID 25961925, 2016). "Tumour lysate pulsing resulted in a significant increase in the expression of MHC and costimulatory molecules as well as of CD83, a marker of phenotypical maturation, CD40 and CCR7." (PMID 26795765, 2016). "Moreover, ascophyllan treatment induced up-regulation of CCR7 in DCs and its ligands CCL19 and CCL21 in spleen in tumor-bearing mice." (PMID 27008707, 2016). "RA-XII inhibited CCR7 expression on 4T1 cells, and downregulating CCR7 level might be one of the mechanisms involved in inhibiting metastasis in RA-XII-treated 4T1 tumour-bearing mice." (PMID 26592552, 2015). "In the present study we demonstrated that LMW HA represents a potent stimulator of migration toward lymph node for human DC obtained from both HD and CRC patients, likely partially involving CCR7/CCL21 axis and inducing resistance to IL-8, a tumor-derived DC chemoattractant." (PMID 25238610, 2014). "CD45RA and CCR7 expression patterns indicated that both LAP+ and LAP− subsets of Foxp3+CD4+ T cells mostly had an effector/memory phenotype in peripheral blood as well as in tumor sites of CRC patients." (PMID 25268580, 2014). "Following inoculation of MB49, Val-boroPro effectively induced tumor eradication in recipients of wildtype bone marrow but not in CCR7−/− chimeras." (PMID 23554941, 2013). "CCR7 was detected in the thymus, lymph nodes, spleen, liver and Hepa 1–6 tumor, but not in the Hepa 1–6 cell line." (PMID 24304581, 2013). "Our data indicate the additional importance of selecting TL with appropriate tissue/tumor migratory properties, rather than CCR7+ naïve or memory TL that migrate to the T-zones of SLO, for treatment of the autochthonous inflammatory tumors that we study." (PMID 21811640, 2011). "CCR7 was expressed by spindle shaped stromal cells in 43% of cases but not by tumor cells in this series." (PMID 21624121, 2011). "Blocking of chemokine receptor CCR2 but not CCR1, CCR3, CCR5, CCR7 or CXCR3 on CTL007 with Abs significantly inhibited tumor cell apoptosis." (PMID 21450101, 2011).
tumor (continued). "The relationship between CCR7 and MMP-9 suggests that these two factors may enhance each other and promote tumor dissemination synergistically." (PMID 21548969, 2011). "It was observed that CXCR4 and CCR7 expression in metastasis tumor was even higher, although no significant distinction was evident." (PMID 20181250, 2010). "Abundant intraepithelial infiltrations of Treg with very high levels of Foxp3 expression and absence of CCR7 expression were also detected in five primary tumours." (PMID 17262084, 2007). "At presentation, only one patient with a CCR7-negative primary tumour had nodal disease but every patient with ‘+++’ staining had advanced neck disease (N2 or N3)." (PMID 17687340, 2007). "Comparisons of TLS statuses within tumor samples showed that naive/central memory and effector memory phenotypes of CD8+ T cells (clusters 1 and 2), which highly expressed memory/stem-like markers including TCF7, CCR7 and IL7R, were enriched in mTLS samples and depleted in imTLS and nTLS samples." (PMID 40335494, 2025). "Analyses of tumor mouse models did not assign predictive value to CCR7 expression in intratumoral cDC1, suggesting that CCR7+ cDC1 may not be involved in forming clusters with CD8+ T cells." (PMID 40667699, 2025). "To probe functionality of initial lymphatic vasculature within the tumor, we measured the expression of CCL21, a lymphatic endothelium-specific cytokine that attracts antigen-presenting cells, T-lymphocytes, and conversely metastatic cancer cells through CCR7 activation." (PMID 39998766, 2025). "No matter whether on HCC clinical specimens and in tumor-bearing mouse models, we still cannot rule out the influence of chemokine axes other than CCR7." (PMID 40685403, 2025). "Cells in cluster 5 expressed homing receptor genes (Sell and Ccr7) but exhibited little to no expression of effector molecule genes (Gzmb, Ifng, and Prf1), suggesting that they do not directly participate in anti-tumor responses." (PMID 39925817, 2025). "Given the extensive involvement of metabolic and signal transduction pathways in tumor cells, we aimed to identify the key components of T24 cells responsible for CAF activation and to determine whether the CXCL14/CCR7/STAT3/ERCC4 signaling axis is involved in this process." (PMID 40898244, 2025). "After all, we could not detect a significant association of the expression of CCR7 and CD45RA with anti-tumor activity or toxicity." (PMID 38318174, 2024). "Consistent with the previous understanding that tumour‐derived CCL19 inhibited the CD8 T cell and promoted lymph node metastasis, we hypothesize NPC tumour cells will release CCL19 and reshape the immunosuppressive TIME of metastatic lymph nodes via CCR7." (PMID 39392128, 2024). "In addition, intra-tumoural CCR7+ DCs, that remain within the TME despite expression of the classic LN-homing chemokine receptor CCR7, may be important, although the precise relationship of these cells to other DC populations is still being discussed." (PMID 38223410, 2024). "Still in the untreated tumor, when compared to NBTXR3 + XRT + αPD1, NBTXR3 + PRT + αPD1 treatment resulted in a significant increase in the expression of activation markers such as Gzmb, Icos, Prf1 (Perforin 1), as well as chemokine receptor (Ccr7), and chemokine ligand (Ccl5) in cytotoxic T cells." (PMID 39354474, 2024). "MiR-21-5p directly targets CCR7, coordinating cancer cell migration, inhibiting its expression, and, therefore, suppressing downstream STAT3, which regulates tumor cell metabolism and NF-κB signaling, mediating neoplasm proliferation, survival, and angiogenesis." (PMID 38542153, 2024). "Administration of anti-PD-L1 antibodies to isolated, tumour antigen-experienced CCR7+ BMDC in vitro did not alter their phenotype, but the addition of recombinant IFNγ upregulated expression of OX40L, PVR and CD40, consistent with the activated Ccr7_DC.2 state." (PMID 38267413, 2024).
tumor (continued). "However, the success of directing tumor-reactive T cells into draining lymph nodes likely depended on the cell type releasing the attracting chemokine, as CCR7-transduced T cells showed similar homing but no therapeutic effect." (PMID 37301772, 2023). "Interestingly, CCR7 staining in tumors was significantly correlated with pre-tumor lymphatic pulsing in FW mice but not in NW mice." (PMID 37801190, 2023). "Therefore, our results demonstrated that CD8 + T cells with CCR7 + and IL7R + had the characteristics of malignant and immune cells, which could lead to tumor progression and immunosuppression." (PMID 37221625, 2023). "The CCL19/21-CCR7 axis can be used to promote NK cell infiltration, and chemokine receptor CCR7-bearing NK cells genetically reprogrammed by cGMP-compliant mRNA electroporation method showed enhanced migratory ability towards their ligands CCL-19 and CCL-21 and offered tumor infiltration." (PMID 36797756, 2023). "In most cases, T-cells (both CD4+ and CD8+) in the tumor microenvironment display an activated phenotype represented by an increased expression of activation markers (i.e., CD69, CD25, CD95, CD44, and HLA-DR) and concomitant decrease in naive T-cells markers (CD45RA and CCR7)." (PMID 37835465, 2023). "Furthermore, when SCC4 tumors were grown in a nude mouse model, CCR7 knockdown reduced tumor growth, inhibited cervical lymph node metastasis and extended survival." (PMID 35203305, 2022). "However, in animals where cDC migration was impaired (Zbtb46dtr::CCR7−/−), this survival advantage disappeared after radiation therapy, and tumor cures were no longer observed." (PMID 35487695, 2022). "In addition, the tumor tissue of the DEN/CCl4-treated WT mice shows a reduction of chemokine receptors levels compared to the surrounding tissue of the same mouse (Ccr5, Ccr2, Ccr7, Ccr1 and Cxcr4)." (PMID 35897689, 2022). "Furthermore, CCR7-expressing tumor cells grew more rapidly than CCR7-negative tumor cells both in vivo within mammary fat pads and in three-dimensional in vitro culture systems." (PMID 35203305, 2022). "Furthermore, both CCR7 expression on tiDC2s and expansion of the dLN migratory DC2s were not lost following CD4 depletion, demonstrating that DC2 migration is upstream of CD4+ T cell infiltration to the tumor." (PMID 34283809, 2021). "The role of TCM cells in anti-tumor immunity may further be highlighted by the observation that CCR7+ TCM cells were found to have near equivalent or even greater levels of cytokine production and cytolytic activity as that of CCR7− TEM cells." (PMID 33572793, 2021). "However, we could not detect any significant differences between patients with high and low H-score for CCR7 regarding ENSAT stage, resection status, hormone secretion, tumor size, Ki67 index, Weiss-Score, or presence of lymph node or distant metastases." (PMID 34830848, 2021). "Additionally, immature DC, when infused, will not traffic to the tumor like mature DC’s do, as fully mature DCs upregulate CCR7 and respond to CCL19 chemotaxis." (PMID 33513928, 2021). "Thus, the tumor microenvironment factors do not inhibit the responsiveness of luminal-B cells to chemotactic cues mediated through the CCR7/CCL21 axis." (PMID 32340161, 2020). "We propose that a panel comprising the markers CD45RA, CCR7, CD95, CD69, CD57, PD-1 as well as CD28, CD40L, and ICOS should be validated in larger cohorts of patients and used to develop a model aiding in the identification of NSCLC patients prone to show tumor regression upon anti-PD-1 therapy." (PMID 31176366, 2019). "In accordance with our previous studies, lung and tumor T cells did not express CCR7." (PMID 30505306, 2018). "Finally, we examined Treg subsets according to the expression of both CD45RA and CCR7, and found that most intratumoral Tregs displayed a CD45RA−CCR7− effector/memory phenotype, whereas non-tumor tissue-derived Tregs displayed largely more CD45RA−CCR7+ central memory phenotype." (PMID 28817117, 2017).
tumor (continued). "However, there was no statistical difference between age, gender and tumor size and the miR-199a-5p or CCR7 expression level." (PMID 27814720, 2016). "In addition, we identify, and confirm functionally, a novel mechanism by which Tregs target to and accumulate within a human tumor microenvironment, through the down regulation of S1PR1, SELL (L-selectin) and CCR7, potentially resulting in greater lymph node retention." (PMID 27228053, 2016). "Additionally, curcumin induced apoptosis in Dectin-1+ cells (M2 phenotype) in a dose-dependent manner without killing CCR7+ cells (M1 phenotype) in splenic MDSCs from tumor bearers." (PMID 27405665, 2016). "CCR7 is mainly expressed on some subsets of CD8+ T lymphocytes, naïve T lymphocytes (CCR7+ CD45RA+) and central memory T lymphocytes (CCR7+ CD45RA−), which may differentiate into CTL to acquire an anti-tumor function." (PMID 27136535, 2016). "For example, NK cells present in tumor-infiltrated peripheral tissues are often enriched in CD56bright CD16neg/dim NK cells; in contrast, an expansion of an unusual subset characterized by a CD56dim CD69+ CCR7+ KIR+ phenotype has been detected in tumor-infiltrated lymph nodes." (PMID 27774094, 2016). "Unlike the REP-expanded tumor-infiltrating lymphocytes (TILs), which are mainly CCR7-negative effector or effector memory cells, the REP T cells that were expanded from peripheral blood mononuclear cells were heterogeneous, and the majority of this population maintained an young phenotype." (PMID 27258611, 2016). "Since expanded γδT cells retain the capacity to secrete pro-inflammatory cytokines (IFNγ, TNFα) and to express, albeit at reduced levels, lymph node-homing markers (CCR7, CD62L), the infusion of tumor-antigen-loaded γδT cells may be followed by a single treatment with zoledronate." (PMID 25101086, 2014). "However, the expression of both CCR7 and CCL21 in gastric cancer may indicate a poorer prognosis through lymph node metastasis illustrating how context/tumor type-dependent chemokine expression may be with regard to prognosis." (PMID 24762633, 2014). "First, none of the ligands for CCR4 and CCR7 had enhanced expression in tumor environment." (PMID 21935436, 2011). "No CCR7+/α-SMA+cells could be observed in normal LN (i.e. without tumor cells) whether from node-negative or node positive axillary LN dissection (not shown)." (PMID 21624121, 2011). "Among the patients with lymph node positive tumors, 3 LN from 2 patients with micro-metastases could not be analysed because of insufficient material left, while for 3 other patients, CCR7 expression could not be assessed in the primary tumor." (PMID 21624121, 2011). "CCR7, expressed in various lymphoid tissues, activates B and T lymphocytes and facilitates tumor cell migration by mediating interactions between tumor cells and chemokines CCL19/CCL21, and may enhance tumor cell anti-apoptotic capacity through regulation of necroptosis-related gene expression." (PMID 40547036, 2025). "Moreover, when CCR7 CD19 t-haNK cells injected into NSG mice inoculated with CCL19-secreting Raji lymphoma cells, tumor control and survival were increased in both local and systemic tumor models compared to mice treated with CD19 t-haNK cells that do not express the CCR7 receptor and control mice." (PMID 41246355, 2025). "However, the precise contribution of CCR7+ DCs to anti-tumour responses, and whether they have a positive or negative effect on disease outcomes remains unclear." (PMID 38267413, 2024). "CCR7 acts as a regulator in the migration of lymphocytes such as dendritic cells, T cells, and B cells to the lymph nodes, while MMP-9 degrades type IV collagen in tumor basement membranes, and extracellular matrix so that tumor cells may invade the surrounding tissues, then metastasis happens." (PMID 37600570, 2023).